CREB1 (cAMP responsive element binding protein 1)
Diseases named in the same sentence as CREB1 in open-access papers (continued):
Sharing a sentence is not in itself a finding about the gene and the disease.
tumor (continued). "Most importantly, compelling evidence demonstrates that CREB1 plays an essential role in promoting tumor development." (PMID 34641874, 2021). "Consistently, the most frequent consequences of suppressing CREB1 by either knockdown or inhibitors are cell death, metastatic defect, failure to form colony and filopodia, and inhibition of tumor growth." (PMID 34641874, 2021). "Such kind of discrepancies is important for understanding distinct functions of CREB1 in different types of cancer and providing guidance for tailored anti-tumor strategies." (PMID 34641874, 2021). "The CAMP responsive element binding protein 1 (CREB1) was evaluated, and the age and the interaction between age/tumour factors were significant and the relative gene expression decreased in WW vs AW (WW < AW)." (PMID 34940589, 2021). "Compelling evidence demonstrates that CREB1 also plays an essential role in promoting tumor development." (PMID 34641874, 2021). "To further confirm the accuracy of the multi-omics analysis, we evaluated CREB1 detected using immunohistochemistry in tumor tissues by using 60 OV commercial tissue microarrays." (PMID 33921660, 2021). "As CREB1 overexpression was found in many tumor types, it is very likely that CREB1 is mainly responsible for controlling these CREB1 concordantly regulated genes in cancer cells." (PMID 34641874, 2021). "Altogether, these data suggest that miR-27a-3p is at least partially involved in the post-transcriptional regulation of CREB1 in the tumor cell line MZ2733RC." (PMID 32300145, 2020). "In RCC, only a limited number of studies evaluated the impact of CREB1 and tumor development and progression." (PMID 32300145, 2020). "Immunohistochemistry was performed to determine p‐CREB1 expression in the 186 primary tumors and matched 160 non‐tumor tissues." (PMID 32832354, 2020). "In this context, CREB1 harbors a high oncogenic potential and is capable to be part of the malignant transformation converting normal cells into tumor cells." (PMID 32300145, 2020). "First, CREB1 protein expression was analyzed in 12 pairs of ccRCC tissues and matched adjacent non-tumor tissues by Western blot, which demonstrated an aberrant expression." (PMID 32300145, 2020). "Confirming recent studies, CREB1 protein was frequently up-regulated (9/12 pairs, 75%) in the tumor tissue compared to matched non-tumor tissue." (PMID 32300145, 2020). "Overall, we revealed that imperatorin not only exerts “cell‐intrinsic” effects to inhibit tumor invasion and metastasis by directly targeting CREB1, but it also exerts “cell‐extrinsic” effects to suppress tumor angiogenesis by inhibiting CAFs‐secreted CCL2." (PMID 32832354, 2020). "Subsequently, split signals of EWSR1, ATF1 and CREB1 in tumor cells of the large lesion were 5%, 2% and 0%, respectively." (PMID 32803839, 2020). "To detect the presence of EWSR1, ATF1 and CREB1, we counted 100 nuclei in tumor cells and that showed a pair of fused and split signals, and calculated the percentage of split signals." (PMID 32803839, 2020). "Noteworthy, in two out of twelve pairs (~17%) CREB1 was down-regulated in the tumor suggesting a different regulation in this CREB1 low subtype." (PMID 32300145, 2020). "MiRNA-122 has been found to target a number of genes linked with tumour progression, including Snail 1 and Snail 2, WNT1, CREB1, and BCL9." (PMID 31979312, 2020). "BC094916 overexpression suppressed Creb1 and Bcl2 transcription to induce cell apoptosis, which suppressed SP 2/0 proliferation and xenograft tumor progression." (PMID 30220882, 2018). "We observed that both cancer cells and tumor vascular ECs display intense nuclear staining of phospho-CREB1, indicating chronic activation of the cAMP-PKA cascade in these cells." (PMID 29775418, 2018). "Statistical analysis indicated that the expression level of CREB1 protein in BCa tissues was significantly higher than in adjacent non-tumor tissues (P<0.001)." (PMID 26844702, 2016).
tumor (continued). "We further examined the expression patterns and subcellular localizations of CREB1 proteins in BCa tissues and adjacent non-tumor tissues by IHC analysis." (PMID 26844702, 2016). "Network analyses of putative asRNA targets using GeneGo Metacore has shown significant over-representation (P-value=8.03e-285) of genes regulated by the CREB1 transcription factor in HPV16+ tumours." (PMID 29263803, 2016). "Like a oncogene, CREB1 is involved in a number of tumor cellular processes such as proliferation, invasion, and metastasis." (PMID 27801665, 2016). "Cell proliferation assays and colony formation assays revealed that CREB1 silencing decreased cell proliferation, suggesting the tumor-promoting function of CREB1." (PMID 27046651, 2016). "After adjusting for age, gender, TNM stage, tumor grade and size, Cox multivariate analyses showed that CREB1 expression is an independent prognostic factor for CRC (HR = 1.953; 95% CI = 1.125–3.389, P = 0.017)." (PMID 27046651, 2016). "Our results indicate CREB1 as a critical transcription factor of RRM2 which promotes tumor aggressiveness, and imply a significant correlation between CREB1 and RRM2 in CRC specimens." (PMID 27801665, 2016). "Recent researches reported that tumor associated genes including Bcl-2, c-fos, and tumor necrosis factor-α (TNF-α) were regulated by CREB1." (PMID 27801665, 2016). "A prognostic model combining CREB1 expression with TNM tumor stage was constructed by logistic regression analysis." (PMID 25825983, 2015). "As expected, the prognostic model is a more powerful predictor than CREB1 expression or tumor stage alone." (PMID 25825983, 2015). "The prognostic model, combining CREB1 expression and tumor stage, displayed more effectiveness than either CREB1 expression or tumor stage alone to predict patients' survival." (PMID 25825983, 2015). "Given the relatively higher HR (hazard ratio) and clearer separation between high-risk and low-risk groups in the survival curves, we suggest that the prognostic model was more effective than CREB1 expression or tumor stage alone to predict patients' outcome." (PMID 25825983, 2015). "The prognostic model was proven to be an independent prognosis predictor and performed better than CREB1 or tumor stage alone." (PMID 25825983, 2015). "Genistein treatments, knockdown of EMP2 gene and double knockdown of CREB1 and EMP2 genes significantly inhibited tumor growth and notably downregulated CREB1 and EMP2 protein levels in the mice xenograft models." (PMID 25940704, 2015). "The coefficients (±standard error) of CREB1 expression and tumor stage were 2.011 (±0.567) and 2.342 (±0.374), respectively, with the constant of –6.740 (±1.135)." (PMID 25825983, 2015). "Hsieh demonstrated that phthalates stimulated the aryl hydrocarbon receptor (AhR) and triggered the cyclic AMP (cAMP)/PKA/CREB1 pathway, which emanated from the phthalated-induced AhR promoted tumor genesis of ER-negative breast cancer." (PMID 23469012, 2013). "Moreover, the IHC results showed higher levels of IL17RB and CREB1 expression in tumours of mice overexpressing CHDH." (PMID 40928004, 2025). "Herei, we found that CREB1 was high-expressed in GC tissues, and CREB1 overexpression reversed the inhibition of GC cell progression mediated by miR-409-3p overexpression, reflecting the tumor promoting role of CREB1 in GC, which was consistent with previous studies." (PMID 39735673, 2025). "Given the role of CREB1 in regulating CENPE, therapies that disrupt the CREB1‐CENPE axis may be particularly effective in inhibiting tumour growth and metastasis in ccRCC patients." (PMID 40794013, 2025). "Leveraging advanced bioinformatics techniques, the identification of 12 crucial genes (ETNK1, BICRA, IL-1R1, KDM3A, ARID2, GSK3β, EZH2, NOTCH1, SMARCA4, FOS, CREB1, CASP3) associated with the tumor-suppressing miR-101-3p network stands out as a notable achievement." (PMID 40074445, 2025).
tumor (continued). "Orthotopic models that more closely mimic the natural tumour environment could provide deeper insights into how CENPE and CREB1 promote tumour progression in a more physiologically relevant context." (PMID 40794013, 2025). "CREB1 has been proven to be involved in many types of tumor development." (PMID 39735673, 2025). "Fusions between members of the FET gene family (EWSR1 and FUS) and genes encoding for the CREB-transcription factor family (ATF, CREB1, and CREM) have been reported in a variety of clinically and pathologically distinct neoplasms of mesenchymal, epithelial and mesothelial origin." (PMID 39031200, 2024). "If an EWSR1::ATF1 fusion is detected in pulmonary myxoid sarcoma with EWSR1::CREB1 translocation, the tumor may be classified as “pulmonary myxoid sarcoma with EWSR1::CREB translocation”." (PMID 38421462, 2024). "Secretion of VEGFC and CCL5 mediated by CRIP1 and CREB1 could reshape the tumor microenvironment into a suitable “soil” which could favor lymphangiogenesis and LM." (PMID 37409440, 2023). "Besides, CREB1 knockdown suppressed xenograft tumor growth in the presence of Imidazole Ketone Erastin (IKE), a potent FIN, and this effect was reversed by SCD." (PMID 37957645, 2023). "More importantly, CREB1 operates as a potent tumor driver in OS." (PMID 37285335, 2023). "To determine whether the tumor suppressive effects of miR‐203a are due to its impact on CREB1 expression, we co‐expressed a miR‐203a mimic and CREB1." (PMID 37565725, 2023). "In addition, upregulation of MITF rescued the dampened tumour proliferative/metastatic properties driven by shRNA-mediated silencing of CREB1." (PMID 36268034, 2022). "The specific mechanism may be CREB1 transcriptional regulation of miRNAs, thus promoting tumour development." (PMID 36522613, 2022). "Similarly, upregulation of an expression network centered on CREB1 and downregulation of a network centered on NF-κB were prominent in the differentially expressed genes common to both subtypes during the spleen-to-tumor transition." (PMID 36480485, 2022). "However, for GBM patients, a significantly higher expression was detected in the tumor patients in accordance with our results, as miR-30e-3p and miR-16-1-3p affecting CREB1 were less abundant in IS T98G cells." (PMID 34157951, 2021). "CREB1 has been implicated in supporting tumor cell proliferation and survival in some types of tumor cells, indicating that CREB1 might be an oncogenic protein that can help tumor cell to proliferate in certain situations." (PMID 34179023, 2021). "Similarly, MIR27B mRNA binds with the 3′-UTR of the CREB1 gene, which blocks estrogen-induced transcription due to lack of inducer transcripts for DNA binding protein suppressing tumor proliferation." (PMID 33920789, 2021). "Another study showed that CREB1 plays a vital role in the tumor progression of upper liver cancer." (PMID 33921660, 2021). "CREB1 was shown to be a target of the tumor suppressor miR-493-5p." (PMID 34830370, 2021). "However, CREB1 mRNA levels were highly comparable in both cell lines pointing to an extensive post-transcriptional regulation of CREB1 in the tumor cell line MZ2733RC." (PMID 32300145, 2020). "Kaplan–Meier survival analysis showed that the patients with high p‐CREB1 expression in their tumors had significantly shorter survival (median survival = 13.0 months) than the patients with low tumor p‐CREB1 expression (median survival = 26.0 months) (log‐rank = 13.28, P < 0.001)." (PMID 32832354, 2020). "Although CREB1 has been reported to play an important role in tumor development and progression in other cancer types, the clinical relevance of CREB1 in ESCC remains unknown." (PMID 32832354, 2020). "Next we asked whether CREB1 expression could improve the prognostic value of tumor stage, therefore a prognostic model combining CREB1 expression with tumor stage was constructed by logistic regression." (PMID 25825983, 2015).
tumor (continued). "Our study identified a novel transcriptional target, which plays a tumor suppressor role, of CREB1." (PMID 25940704, 2015). "CREB1 was also regarded as an oncogene that promoted tumor cell growth and proliferation." (PMID 23469012, 2013). "Here our findings reveal a metabolic mechanism for CREB1-mediated tumor cell survival, and also suggest that targeting GCLM or oxidative stress potentially could be a therapeutic approach for treatment of tumors with relatively high expression of CREB1 family proteins." (PMID 34179023, 2021). "However, CREB1 functions like a tumor suppressor in other cancer types." (PMID 27801665, 2016). "Finally, in a multivariate Cox model including sex, age, tumor grade, T stage, lymph node status, c-Met expression, and CREB1 expression, we found that the overexpression of CREB1 expression was a good independent prognostic factor for overall survival in patients with BCa (P=0.039)." (PMID 26844702, 2016). "Thus, CCDC6 would work as tumor suppressor in inhibiting the CREB1-dependent gene expression." (PMID 25970781, 2015). "Thus the prognostic model, which has been used in previous studies, was constructed in an attempt to test whether CREB1 expression could improve the predictive power of the conventional TNM tumor stage." (PMID 25825983, 2015). "The downregulation of MCPIP1 expression promotes a tumor-promoting microenvironment through the coordinated activation of the β-catenin, STAT3, and CREB1 pathways." (PMID 41955682, 2026). "Lactylated CREB1 promotes HMGB1 transcription and subsequent exosomal secretion into the tumor microenvironment." (PMID 42212318, 2026). "It hinders cAMP response element binding protein 1 (CREB1) binding to ribosomal protein S6 kinase A3 (RPS6KA3), thereby inhibiting tumor growth." (PMID 41181701, 2025). "Among 12 tumors with known fusion partners, the fusions partner was CREB1 in 6 cases (50%), CREM in 4 tumors (33%), ATF1 in one tumor (8%) and PBX3 (8%) in another tumor." (PMID 40748380, 2025). "Through CREB1-mediated PI3K/Akt/mTOR signaling, UCA1 upregulates the expression of CREB1, competitively binds miR-582, and accelerates EMT pathway, thereby boosting tumor metastasis." (PMID 39119480, 2024). "The network of the most promising miRNA-target interactions showed that several tumor suppressor and oncogenic miRNAs target and regulate critical genes, including MYC, CREB1, TIMP3, CCNE1, and TGFB1, which were shown to be involved in WT pathogenesis." (PMID 39473825, 2024). "Cluster 0 expressed several tumour-related transcription factors such as ELK4, CREB1, cJun, JunD, KLF6, ETS-1 and ZNF217." (PMID 38480935, 2024). "Immunohistochemical staining and Western blotting were used to observe the expression of risk model factors PRR11, KIF11, RACGAP1 as well as the potential common transcription factors YY1, CREB1 and SUZ12 in HCC tissues and para-tumor tissues." (PMID 39530087, 2024). "Their research revealed that UCA1 upregulates several tumour‐promoting genes such as CAMP responsive element‐binding protein 1 (CREB1), B‐cell lymphoma 2 (BCL2) and Ras‐related protein Rab‐22A (RAB22A) by sponging miR‐204‐5p, which is a tumour suppressor." (PMID 38506091, 2024). "Further experiments showed that recombinant REG4 (rREG4) activated CREB1 and upregulated SRGN expression in tumour cells." (PMID 38862740, 2024). "Some targets, such as DLX4, NDRG3, WNT1, MYC, CREB1, and SIRT6, are involved in tumor or cell proliferation." (PMID 39618816, 2024). "REG4 activates CREB1 by interacting with its receptor, EGFR, in tumour cells, resulting in increased SRGN expression." (PMID 38862740, 2024). "In comparison to two control sgRNAs targeting nonessential genes Rosa26 and H11, two independent sgRNAs targeting Mc1r blocked α-MSH-induced CREB1/ATF1 phosphorylation and slowed tumor growth." (PMID 37714844, 2023).
tumor (continued). "The IHC staining of the xenograft tumor tissues showed that CREB1 knockdown decreased the level of 4-HNE, a marker of lipid peroxidation, and that SCD overexpression restored the CREB1 knockdown effect." (PMID 37957645, 2023). "Such dataset outcomes illustrate for the first time that the anti-tumour effect of miR-585-5p in GC is due to direct simultaneous inhibition of MITF, CREB1 and MAPK1 expression." (PMID 36268034, 2022). "Meanwhile, exosomes containing ELFN1-AS1 siRNA1 reduced the expression of CREB1, CD206, vimentin and N-cadherin, and increased the level of E-cadherin in tumor tissues, compared with the 143B + MExo group." (PMID 35785218, 2022). "Only a limited number of CREB1-targeted genes, including CCNA1, CCND1, BCL2, MMP2, MMP9, GSK3A, were shown to contribute to tumor development." (PMID 34641874, 2021). "Moreover, the analysis of an TMA consisting of 453 consecutive RCC tumors revealed a weak, but significant correlation of CREB1 with tumor stage, tumor grade TNM V and TNM L. To further validate the results of this study, the analyses of additional cohorts could be of interest." (PMID 32300145, 2020). "In light of that the pTNM stage system integrates the clinical significance of the tumor, lymph node and distant metastasis, only pTNM stage, CEA, CA19-9, CREB1, CCAR1 and JNK1 were incorporated into the multivariate analyses." (PMID 30523220, 2018). "As a target gene of CREB1, RRM2, except for providing dNTPs for cell proliferation, cooperates with a number of oncoproteins to promote tumor development." (PMID 27801665, 2016). "On the contrary, proliferation-promoted genes such as CTNNB1, CREB1, CREB5, and TCF7L2 were up-regulated 3.65-, 2.63-, 2.87-, and 5.75-fold respectively in tumor tissues." (PMID 23285163, 2012). "Overall, we have identified CREB1 as a positive transcriptional regulator for CENPE in ccRCC in vitro, directly binding to its promoter region and promoting its expression, thereby contributing to the upregulation of CENPE in tumour progression." (PMID 40794013, 2025). "We hypothesised that CHDH activates CREB1 by promoting the expression of IL17RB, which may reveal a novel mechanism by which CHDH promotes tumour progression." (PMID 40928004, 2025). "Notably, when CREB1 was silenced, these oncogenic effects of CENPE were significantly diminished, further supporting the essential role of CREB1 in mediating CENPE's tumour‐promoting effects in ccRCC." (PMID 40794013, 2025). "Differences in molecular fusion type (EWSR1/CREB1 versus EWSR1/ATF1), tumour burden at relapse, and prior treatments may partly explain the variability in responses across cases." (PMID 41020828, 2025). "Key transcription factors (TFs), such as CREB1, CIITA, and ICAM1, regulate the expression of immune-related genes, including those involved in antigen processing and HLA class I/II expression, thereby influencing tumor antigen presentation." (PMID 41312385, 2025). "Five transcription factors (CREB1, CTCF, YY1, E2F1, MYBL2) were significantly elevated with tumor progression in HCC, indicating that these potential transcription factors may be responsible for the upregulation of H3–H4 histone chaperones in HCC." (PMID 38561384, 2024). "Furthermore, AMPK also regulates glucose metabolism with cAMP response element binding protein-1(CREB1), and promotes glycolysis in tumor cells." (PMID 38778409, 2024). "While numerous oncogenes have been identified as enhancers of tumor metastasis through the promotion of EMT, a subset of oncogenes, such as CREB1, MYC and FBXO22 (F-box protein 22), has been observed to concurrently facilitate proliferation while inhibiting EMT." (PMID 39883338, 2024). "Activation of the CREB1/CEBPB axis can promote the expression of M2 macrophage markers, and the precise identification of crucial factors governing CREB1/CEBPB axis-mediated M2 macrophage regulation within the tumor microenvironment remains elusive." (PMID 38243273, 2024).